ERBB2 (erb-b2 receptor tyrosine kinase 2)
Diseases named in the same sentence as ERBB2 in open-access papers (continued):
Sharing a sentence is not in itself a finding about the gene and the disease.
cancer (continued). "As well as identifying high frequency, differentially expressed genes, including known cancer genes such as PIK3CA and AURKA, we also used high amplitude regions to locate additional known (e.g. ERBB2 and CCNE1) and potential oncogenes." (PMID 20386695, 2010). "A transcript of 383 bps corresponding to the CXCL12 gene was detected in the less aggressive carcinoma cell lines MCF-7 and PMC42, in the normal cell line HB4a and in the modified normal cell line HB4aC3.6 with ERBB2 overexpression." (PMID 20109227, 2010). "Aggressive BT474 and SKBR3 cancer cells where ErbB2 is overexpressed, MCF10A immortalised ductal cells and non-invasive MCF-7 cancer cells which express low levels of ErbB2, both in their naive state and when forced to mimic aggressive behaviour, were used." (PMID 19133120, 2009). "ErbB2 has been shown to increase VEGF protein production in cancer cell lines, xenografts, and in human cancers." (PMID 18320059, 2008). "In these cancers, AP-2 transcription factors are involved in ERBB2 overexpression, and AP-2 levels are correlated with p185c-erbB-2 levels." (PMID 12942124, 2003). "The ErbB receptor family includes specific transmembrane tyrosine kinase proteins: epidermal growth factor receptor, also known as ErbB1; ErbB2, also known as HER2; ErbB-3; and ErbB-4, all of which are overexpressed to varying degrees in human cancer including HNSCC." (PMID 40675157, 2025). "This pattern of ERBB2 and EGFR co-expression in a subset of cancer cells may be of clinical significance as elevated EGFR expression can promote T-DXd resistance by suppressing T-DXd internalization." (PMID 41422272, 2025). "We conducted an initial filtering step to ensure that all datasets contained clinical-level metrics such as ER Status (Positive or Negative), ERBB2 positive, cancer grade, death, cancer subtype (PAM50), and years to outcome." (PMID 40841370, 2025). "Additionally, combination treatments targeting EGFR, ERBB2, and downstream PI3K/Akt and Ras pathways have shown downregulation of these cancer targets, along with reduced expression of JAK, STAT, and FAK1." (PMID 41024300, 2025). "In response to anti-EGFR therapy resistance, HER2 (Human Epidermal Growth Factor Receptor) therapy was developed (amplified and/or overexpressed ERBB2/HER2 triggered constant signals for cell division and survival, driving cancer progression)." (PMID 41465541, 2025). "Survival remained lowest for Black patients with hormone receptor–positive/ERBB2-negative or hormone receptor–negative/ERBB2-positive cancer and was not affected by GCC receipt." (PMID 40009385, 2025). "ERBB2 activating alterations were detected in 6.6% (n = 28,508) of tumors in the overall cohort and were most prevalent in gastroesophageal carcinoma (GEC; 18.1%), bladder (18.0%), salivary gland (14.1%), breast (12.7%), and uterine (12.1%) cancers." (PMID 40178042, 2025). "Unlike carcinomas where HER2 is predominantly expressed on the cell membrane, HER2 is predominantly identified in the cytoplasm of malignant osteoblasts and its expression occurs in the absence of erbB2 gene amplification." (PMID 39958231, 2025). "HPV can upregulate ERBB family receptors, enhancing proliferation and survival of cancer cells, and HPV E6/E7 might cooperate with ErbB-2/HER2 receptors to trigger cellular transformation through D-type cyclins in CD." (PMID 39791702, 2024). "Basal cells with ERBB2 overexpression demonstrated increased sensitivity to RC48 in vitro and in vivo, indicating that ERBB2 expression mediates RC48’s therapeutic efficacy against cancer." (PMID 39840049, 2024).
cancer (continued). "In addition, Moreover, CAR-NK cell therapy targeting ROBO1, ErbB2/HER2, EGFR, EpCAM, and MUC1 are currently undergoing clinical studies in many cancer types." (PMID 38263004, 2024). "The nCounter v2 Cancer CN Assay panel consists of 87 target genes and is intended for CNV genotyping of tumors with various profiles of aberrations in the PIK3CA, AKT, PTEN, BRCA, ERBB2, and MYC genes." (PMID 39409874, 2024). "A recent study demonstrated that a liposome-based cancer vaccine containing ErbB-2 peptide and ovalbumin peptide OVA323-339 generated a rapid and high-titer anti-ErbB-2 antibody response in mice, increasing specific humoral immune responses by 7.3-fold in just 7 days." (PMID 39204073, 2024). "The rate of pCR was higher in triple-negative and ERBB2-positive cancers than in luminal-type estrogen receptor–positive, ERBB2-negative cancers (45% [5 of 11] vs 5% [2 of 38]; P < .001)." (PMID 38578640, 2024). "Thirdly, PROTAC is a novel technology that could specifically target any protein of interest, such as cancer cell surface markers (such as EGFR, ERBB2, and PD-L1), and induce its ubiquitination proteasome degradation." (PMID 39596025, 2024). "Intriguingly, however, HET/no pCR tumors displayed the same high level of PI3K/ERBB signature enrichment compared with the non-HET/pCR group despite a lower fraction of ERBB2-amplified cancer cells." (PMID 38300710, 2024). "Despite lower overall ERBB2 expression, HER2-HET tumors retained levels of PI3K/ERBB pathway activation equivalent to those in non-HET/pCR cancers, likely due to increased expression of downstream pathway components including MYC and EIF4EBP1." (PMID 38300710, 2024). "It has been suggested that inhibiting the TGF‐β/ErbB2 (also known as HER2) pathway may reduce the progression and metastasis of certain cancers." (PMID 39479720, 2024). "The interplay between ERBB2 and its direct targets MYC, PTEN, and BCL2 creates a robust network that collaboratively impacts cancer cell biology by promoting proliferative signaling, evading growth suppressors, resisting cell death, and facilitating invasion and metastasis." (PMID 39409883, 2024). "DE carcinomas had ERBB2 expression levels which were very close to those of 2+ WA carcinomas, suggesting that transcriptomic expression may correlate with 2+ HER2 protein staining with IHC." (PMID 38893129, 2024). "Higher epithelial immunoreactivity for ERBB2 was observed in malignant tumors compared to benign lesions, although not necessarily alongside higher gene expression, or gene amplification." (PMID 37219601, 2023). "Such ERBB2-low status was associated with slightly improved overall survival and had a lower density of TILs compared with ERBB2-negative cancer." (PMID 37686072, 2023). "Upon inhibition of ERBB2, they deduce that ERBB4 may take over as the dominant pathway for cancer growth." (PMID 37072406, 2023). "Nevertheless, antibody‐based therapy of cancer has achieved significant success in the last years and MABs against EGFR (cetuximab, panitumumab), ERBB2 (trastuzumab, pertuzumab), and ERBB3 (patritumab, seribantumab, lumretuzumab) are used to treat various type of cancer." (PMID 37341059, 2023). "Indeed, the EGFR and ERBB families (ERBB2, ERBB3 and ERBB4) were also ranked in the top 10 cancer driver targets in the transcriptional networking, suggesting their roles in uPAR-mediated tumorigenesis processes were highly anticipated." (PMID 37895906, 2023). "ErbB2 was phosphorylated in implanted cancer cells where tumors formed but was absent in the redirected cells." (PMID 36765535, 2023).
cancer (continued). "Only the expression profiles of CTA genes from the known TAA (NY-ESO-1 and MAGE-A12) and BIRC5, but not ERBB2, displayed elevated cancer expression with low healthy tissue expression." (PMID 36943460, 2023). "Multiple cancer–related genomic alterations, but no ERBB2 amplification, were present in the cfDNA samples from patients PMB2.30 and PMB2.26, classified as HER2‐." (PMID 38046436, 2023). "Interestingly, in some cancer cells, STAT1 can negatively regulate ERBB2/Neu-dependent transformation." (PMID 37669313, 2023). "In our meta-analysis, we identified six genes with high mutation prevalence in brain metastases, of particular interest for their potential role in brain metastatic process and resistance to first-line anti-cancer drugs: ESR1, ERBB2, EGFR, PTEN, BRCA2 and NOTCH1." (PMID 36980614, 2023). "Among the grand range of extracellular receptors usually targeted in cancer therapy, the Human Epidermal Growth Factor Receptor 2 (EGFR2, also known as ERBB2 or HER2) is largely investigated, since its aberrant expression correlates with different malignancies." (PMID 37375741, 2023). "Furthermore, siRNAs against the ERBB2 gene have also shown promising results in overcoming resistance to trastuzumab and lapanitib in HER-2-positive cancer cell lines." (PMID 37108234, 2023). "The ErbB2-redirected CD19 CAR T cells, moreover, showed a 100-fold superior selectivity in targeting cancer cells versus healthy fibroblasts, which was not the case for the ErbB2 CAR T cells." (PMID 36672182, 2023). "Stable cfDNA levels, normal ERBB2 copy number, and the absence of TERT C228T mutations indicate a stable cancer status." (PMID 37945655, 2023). "Importantly, our findings have wider implications against other cancers with aberrant upstream receptor activation, as SNAI2 can work together with oncogenes such as RAS and ERBB2 to enhance tumorigenicity." (PMID 37228489, 2023). "Among genes (RB1, ERBB2, CTNNB1) identified by method CPGA-SMCMN, although they are not enriched in a biological pathway with any other identified genes, they have been reported to be important cancer related genes." (PMID 37221474, 2023). "Since EGF can bind to receptors other than EGFR, such as ErbB2 (HER2), ErbB3 (HER3), and ErbB4 (HER4) across most cancer contexts, and is a key player in cancer metastasis, it is likely that the EGF-associated mechanisms driving EMT are distinct from those regulating MHC I expression." (PMID 38067396, 2023). "In ERBB2+ cancers regardless of the tissue of origin, many ERBB2+ cancers are resistant to ERBB2-targeted therapy." (PMID 37359373, 2023). "Taken together, the CD19-CAR T cells can be efficiently redirected by the CD19-4D5scFv protein against the ErbB2high cancer cells in vitro and in vivo, without attacking the human fibroblasts with the physiological ErbB2 levels." (PMID 36672182, 2023). "By optical genome mapping, the de novo rare variants and genomic alterations are not different between the wildtype, vector, and ERBB2 mRNA-destabilized cancer." (PMID 37359373, 2023). "The development of CARs has led to searching for new targets for cancer therapy, especially for histologies without ERBB2 and HR expression, such as TNBC." (PMID 36900394, 2023). "ERBB2-low status was associated with slightly improved overall survival (≤2% difference at 5 years) compared with ERBB2-negative cancer." (PMID 36821125, 2023). "The attenuation of erbB2 phosphorylation serves as a biomarker of redirection though not as a mechanism of cancer cell redirection." (PMID 36765535, 2023). "We extended these data to compare if destabilization of the ERBB2 transcript and protein in cancers does reprogram the gene expression of cancers toward the normal human lung gene expression pattern." (PMID 37359373, 2023). "The most frequently amplified genes in all cancers are MYC, EGFR and ERBB2 (HER2)." (PMID 37298484, 2023).
cancer (continued). "ERBB2-overexpressing cancers in the genomic classification are HER2 positive with or without ER positivity in the clinical/immunohistochemical classification." (PMID 37345027, 2023). "Indeed, four proteins (P08581|MET, P21860|ERBB3, P04626|ERBB2, and P25445|TNR6) from HCT116-specific group and one protein (P46531|NOTC1) from DKO1-specific group are oncogene products (cancer driver score = 4)." (PMID 36639722, 2023). "We selected ERBB2 for further investigation because it plays a unique function in ERBB complexes as a dominant binding partner that drives prolonged signaling and, in some cancers, behaves as an oncogene." (PMID 37669313, 2023). "Likewise, zenocutuzumab, an ERBB2/ERBB3 (HER2/HER3) bispecific antibody, is under evaluation in clinical trials for patients with NRG1-positive fusions in cancer and has a 34% ORR." (PMID 37958963, 2023). "It is characterized by a lack of estrogen receptors (ER), progesterone receptors (PR) and epidermal growth factor receptor 2 (HER2/ErbB2), therefore, no targeted therapies against these proteins are useful to treat this carcinoma." (PMID 36672233, 2023). "This suggests a further negative prognostic role of ErbB2 in the induction of antioxidant genes, which can lead to the protection of cancer cells from high-dose oxidative damage induced by anticancer therapies." (PMID 35372019, 2022). "Both ERBB2 and FGFR4 have been shown to activate ERK and/or Akt in some contexts such as cancer." (PMID 35921893, 2022). "ErbB-2 oncogene contributes to PC progression by regulating numerous signalling pathways, including AKT, ERK1/2 and STATs, by positively influencing cell survival, migration, and proliferation of cancer cells." (PMID 36468011, 2022). "In the present study, we aim to explore the molecular landscape of ERBB2 alterations in solid tumors by next-generation sequencing (NGS), which will provide additional evidence for the panorama of these therapeutic targets in the Chinese cancer population." (PMID 35911441, 2022). "Although ErbB2 and ErbB4 play an important role in NRG1-promoted cardiac repair, overexpression of ErbB2 receptor subunits can promote uncontrolled cancer growth (Wadugu and Kühn, 2012), which would be the greatest limitation of clinical interventions to achieve myocardial regeneration with ErbB2." (PMID 36120374, 2022). "The sensitivity of the phenocopy signatures in mutation-negative cancer cell lines was on par with DNA alterations for EGFR, BRAF, and MAPK, and better than DNA alterations for PI3K-AKT, PARP/HRD, ERBB2, MTOR, and JAK." (PMID 36253482, 2022). "Patients who received radiotherapy for BRM were more likely to have TNBC or ERBB2-positive cancer than HR-positive/ERBB2-negative cancer (P < .001) and were younger than those who did not receive radiotherapy for BRM (P < .001)." (PMID 35960523, 2022). "In addition, pan-cancer transcriptomic data validated the close relationship between GG and AAG metabolism-related genes and ERBB2 expression." (PMID 35990657, 2022). "The importance of genomic sequencing is apparent with the identification of rare genetic subtypes of cancer, such as the patients presented here with ERBB2 mutant, non-amplified mBC." (PMID 35181666, 2022). "By comparing focal SCNAs in matched NSCLC-BM pairs, we identified putative BM-driving alterations affecting multiple cancer genes, including several potentially targetable alterations in genes such as CDK12, DDR2, ERBB2, and NTRK1, which we validated in an independent cohort of 84 BM samples." (PMID 36561283, 2022). "This study shows a potential involvement of the ErbB2/ErbB3 pathway in CSC generation and could lead to new insight into the mechanism of tumorigenesis and the way of cancer prevention." (PMID 35177646, 2022).
cancer (continued). "Although previous studies concluded that S100A4 could interact with the following membrane receptors, including RAGE, EGFR, ERBB2, TLR4, and IL10R, these findings were derived from the nervous system or cancer-related studies." (PMID 36361563, 2022). "The molecular changes manifested by a cancer cell provide the opportunity for personalised treatment which is exemplified by the use of inhibitors like trastuzumab and lapatinib to treat cancer patients with amplifications of the RTK ERBB2." (PMID 36153371, 2022). "The increased Src activity found in cancer cells can be caused by multiple factors, including an enhanced expression of Src activators, frequently found in cancer, such as integrins, EGFR, the constitutively active mutant form EGFRvIII, HER2 or ErbB2 or other RTKs." (PMID 36217026, 2022). "Statistically, 70% of cancer patients show hormone-receptor-positive/ERBB2-negative phenotype, while 15% to 20% are ERBB2-positive and another 15% have triple-negative tumors (TNBC) missing all three standard molecular markers." (PMID 35209095, 2022). "Interestingly, other cancer patients who suffered from COAD, KICH, KIRC, THYM, and READ also presented more amplification of the ERBB2 gene, had a favorable prognosis of overall survival and disease-free survival." (PMID 36172165, 2022). "In our study cohorts, g3mclass automatically recognized cancers unlikely to be present in the reference, i.e., ERBB2 mRNA + (class 2 and higher) and ESR1 mRNA + (class 1 and higher)." (PMID 36335194, 2022). "The overexpression and/or mutations of epidermal growth factor receptor (EGFR) family proteins, i.e., EGFR (HER1), ERBB2, ERBB3 and ERBB4, are often found in multiple types of cancer cells and are considered to be a significant prognostic indicator in the clinical intervention of cancer." (PMID 35163685, 2022). "Besides, seven cancer genes including CTNNA1, ERBB2, MECOM, NFE2L2, PRKCI, TRAF3, and ARHGAP26 were found to be fusion genes." (PMID 34505199, 2022). "It is known that ERBB2 and AREG stimulate glucose uptake and could regulate mitochondrial functions through switching cancer cell metabolism from OXPHOS to glycolysis to enhance cell growth." (PMID 35328408, 2022). "We reviewed the results of gene profiling targeting 160 cancer-related genes in breast (N = 90) and non-breast (N = 19) cancer tissue, and compared the ERBB2 CN results with the IHC/FISH scores." (PMID 33710417, 2021). "Human epidermal growth factor receptor 2 (HER2; also called Her-2/neu or ErbB2) is a member of the transmembrane epidermal growth factor receptor family and is one of the most studied TAAs for cancer immunotherapy." (PMID 33800608, 2021). "It is not surprising finding in our results that uPA-uPAR system is not consistently involved in ERBB2-amplified cancer since an earlier report showed that ERBB2 overexpression did not affect uPA expression." (PMID 34535639, 2021). "ERBB2 forms a heterodimer with another ERBB family member to form a more stable and strong signaling function and is considered to be an important therapeutic target for cancer." (PMID 33732282, 2021). "Furthermore, the phosphorylation levels of EGFR, ERBB2, GRB2, and SRC were significantly reduced in the PAF-AH 1B2 KD cancer cells as determined by the Luminex assay and western blot data." (PMID 34930255, 2021). "AFP binding to ErbB2 can also enhance MUC4 interactions with ErbB2, ErbB3, and neuregulin, increase the phosphorylation of the ErbB2 complex and result in enhancing cancer cell proliferation, migration, invasion and inhibition of apoptosis through activating ERK and AKT signaling pathways." (PMID 33718192, 2021). "Unlike ERBB2+ cancers, those that do not overexpress ERBB2 promote anti-apoptosis and metastasis through other mechanisms and will not respond to ERBB2 inhibitor treatment." (PMID 33670942, 2021).